LCN2 (lipocalin 2)
Diseases named in the same sentence as LCN2 in open-access papers (continued):
Sharing a sentence is not in itself a finding about the gene and the disease.
pneumonia (34 papers, 2009 to 2026). An acute, acute and chronic, or chronic inflammation focally or diffusely affecting the lung parenchyma, caused by an infection in one or both of the lungs (by bacteria, viruses, fungi, or mycoplasma.). "In experimental models of pneumonia or sepsis, LCN2 deficiency increases bacterial proliferation and lowers host survival 13-17." (PMID 36923935, 2023). "The protein lipocalin 2 (LCN2) (also known as neutrophil gelatinase-associated lipocalin, siderocalin, or 24p3) functions as a mediator in several diseases associated with cachexia, including cancer, pneumonia, and kidney disease." (PMID 36973755, 2023). "In this study, we investigated the role of LCN2 and its underlying mechanism of action in LPS-treated LCN2-deficient mice with recombinant LCN2 (rLCN2) as well as pneumonia patients." (PMID 36923935, 2023). "LCN2 has recently been recognized as a sensitive biomarker for the diagnosis of severe bloodstream infection and pneumonia caused by Streptococcus pneumoniae." (PMID 32659386, 2020). "The importance of lipocalin-2 in sequestering iron in the lung is highlighted by the observation that pneumonia caused by intratracheal instillation of E. coli is aggravated in lipocalin-2 knock-out mice." (PMID 30609678, 2019). "In this study, we investigated that LCN2 is an inflammatory mediator that is elevated in LPS-treated mice and in patients with pneumonia." (PMID 36923935, 2023). "Circulating proinflammatory cytokines and LCN2-positive macrophages were prominently increased in the BALF of pneumonia patients." (PMID 36923935, 2023). "So, the present study strongly suggests that LCN2-targeting the polarization of macrophages has potential advantages and therapeutic targets for acute lung injury or pneumonia." (PMID 36923935, 2023). "It has been confirmed that bacterial infectious diseases, such as pneumonia and bronchitis, can result in the overexpression of plasma LCN2." (PMID 35610759, 2022). "We find that LCN2 is crucial to reducing mortality from A. baumannii bacteremia and inhibits dissemination of the pathogen during pneumonia." (PMID 36054235, 2022). "Because both bacterial and autoimmune inflammation can induce the overexpression of LCN2, we compared LCN2 expression in children with infectious diseases, such as pneumonia and bronchitis, and children with ISS." (PMID 35610759, 2022). "As VAP and bacteremia are the most frequent and formidable presentations of A. baumannii infection, the role of Lcn2 in a murine model of pneumonia was also assessed." (PMID 36054235, 2022). "Together the results of this study reveal that nutritional immunity, and specifically expression of LCN2, is essential to controlling the outcome of A. baumannii bacteremia and pneumonia." (PMID 36054235, 2022). "In contrast, during pneumonia Lcn2-/- mice had increased bacterial burdens in all organs evaluated, suggesting that LCN2 plays an important role in inhibiting the survival and dissemination of A. baumannii." (PMID 36054235, 2022). "LCN2 is highly expressed in vivo, and in its absence infection outcomes are exacerbated in murine models of both A. baumannii bacteremia and pneumonia." (PMID 36054235, 2022). "Plasma LCN2 expression in children with pneumonia and bronchitis (118.6 ± 2.09 ng/ml) was significantly higher than that in children with ISS (26.01 ± 3.06 ng/ml) (p = 0.001)." (PMID 35610759, 2022). "The results from these in vivo studies reveal that LCN2 has differing impacts on the outcome of A. baumannii bacteremia and pneumonia in mice, suggesting a complex role in the innate immune response to this pathogen." (PMID 36054235, 2022). "Notably, we found that LCN2-positive cells are more prominently observed in alveolar macrophages than neutrophils in the BALF of pneumonia patients." (PMID 36923935, 2023).
pneumonia (continued). "In addition to increase of iron-stained macrophages in pneumonia patients, increased iron-stained macrophages and oxidative stress in LPS-treated mice were inhibited by LCN2 deletion." (PMID 36923935, 2023). "Based on these findings, we hypothesize that LCN2 deletion could protect against pneumonia by inhibiting inflammation and oxidative stress." (PMID 36923935, 2023). "Lipocalin 2 has been shown to be effective against Escherichia coli causing pneumonia, and mutant mice lacking lipocalin 2 were more susceptible to Klebsiella pneumoniae infections." (PMID 37251385, 2023). "In addition to H&E staining, many LCN2-positive cells were significantly increased in BALF slides from pneumonia patients." (PMID 36923935, 2023). "Conversely, Lcn2-deficient mice failed to control the survival and dissemination of A. baumannii during pneumonia, where higher bacterial burdens were recovered in the kidneys, heart, liver, spleen, lungs, and blood." (PMID 36054235, 2022). "In particular, lipocalin-2 (Lcn2) is a bacteriostatic peptide that inhibits bacterial iron-sequestering siderophores and has previously been demonstrated to protect mice from E. coli-induced pneumonia." (PMID 35141503, 2022). "Among the 46 metabolic pathways-related proteins (28 up-regulated and 18 down-regulated), alpha-enolase (ENO1), neutrophil gelatinase-associated lipocalin (LCN2), and Acetyl-CoA acetyltransferase (ACAT1) have been found to be related to pathogens-induced pneumonia." (PMID 36387401, 2022). "Indeed, various biomarkers, including C-Reactive Protein, procalcitonin, lipocalin-2 and tumor necrosis factor-related apoptosis-inducing ligand have been evaluated for their ability to differentiate these pneumonia etiologies." (PMID 35115016, 2022). "LCN2 had a potential protective effect against Escherichia coli-induced pneumonia." (PMID 36387401, 2022). "Moreover, salmochelin and yersiniabactin siderophore production and its interaction with Lipocalin 2 determined the replicative niche of Klebsiella pneumoniae in a mice Pneumonia model." (PMID 30071030, 2018). "Alternatively, redundant signaling pathways may be activated during pneumonia such that inflammatory signaling by Lcn2 is dispensable." (PMID 27624128, 2016). "In Escherichia coli (E. coli)-induced pneumonia rodent models, MSCs improved bacterial clearance by secreting antimicrobial peptide LL-37, antibacterial protein lipocalin 2 (LCN-2) and keratinocyte growth factor (KGF) directly against bacteria or by enhancing macrophage phagocytosis." (PMID 27809910, 2016). "Whether Ent production stimulates Lcn2-dependent inflammation during pneumonia remains to be determined." (PMID 19834550, 2009). "Notably, pneumonia patients had significantly higher serum LCN2 levels than control subjects." (PMID 36923935, 2023). "Plasma LCN2 expression was significantly higher in children with pneumonia and bronchitis than in children with ISS, suggesting that the increased LCN2 levels in children with ISS cannot be attributed to general bacterial infectious diseases." (PMID 35610759, 2022). "In the present study, the wild-type mice had a significantly lower pulmonary and spleen bacterial load in a pneumonia model with E. coli HB101 and H9049 at 48 hours compared to the Lcn2 knock-out mice." (PMID 20633248, 2010). "Since Ent is dispensable for growth during pneumonia from KPPR1, iron sequestration by Lcn2 cannot account for the observed growth inhibition." (PMID 19834550, 2009). "To analyse whether LCN2 is upregulated in ISS because of infectious diseases, we compared LCN2 expression between children with ISS and children with pneumonia and bronchitis." (PMID 35610759, 2022).
renal fibrosis (33 papers, 2014 to 2026). A final common manifestation of a wide variety of chronic kidney diseases characterized by glomerulosclerosis and tubulointerstitial fibrosis. "Although the effect of GP1 on renal fibrosis mimicked the effect of global genetic inactivation of Lcn2, it did not improve renal function or inflammation." (PMID 33510370, 2021). "Moreover, although the effect of NGAL pharmacological blockade using GP-1 on renal fibrosis mimicked the effect of global genetic inactivation of Lcn2, it did not improve either renal inflammation or function." (PMID 36510294, 2022).
colon carcinoma (32 papers, 2008 to 2025). "To explore possible influence of menopausal status on the associations between LCN2 and colon cancer, we have conducted a sensitivity analysis examining data from postmenopausal women only." (PMID 39511728, 2025). "In this prospective cohort study, pre‐diagnostic LCN2 concentrations were positively associated with colon cancer, particularly occurring in the proximal colon." (PMID 39511728, 2025). "The association between LCN2 and colon cancer risk was found in women (adjusted IRR [95% CI], 1.66 [1.20–2.30]), but not in men (adjusted IRR [95% CI], 0.85 [0.58–1.22], P difference <.01)." (PMID 39511728, 2025). "Overall, these data suggest that pre‐diagnostic LCN2 concentrations were positively associated with colon cancer, particularly occurring in the proximal colon, in women and among individuals with abdominal adiposity." (PMID 39511728, 2025). "Here, using data from the European Prospective Investigation into Cancer and Nutrition cohort (EPIC), the authors show that higher levels of circulating LCN2 are associated with an increased risk of colon cancer in women." (PMID 39511728, 2025). "Future studies are warranted to replicate these findings explore the potential of LCN2 as an early risk biomarker for colon cancer and elucidate the mechanisms behind the observed sex‐ and site‐specific associations." (PMID 39511728, 2025). "Our study further revealed an association between elevated LCN2 and risk of colon cancer in participants characterized by abdominal adiposity." (PMID 39511728, 2025). "Further studies combining lines of research from animal models and humans would be warranted to characterize the pathophysiological properties of LCN2 and explore its potential mediating role on the association between adiposity and colon cancer." (PMID 39511728, 2025). "In summary, in this prospective cohort study, higher pre‐diagnostic concentrations of LCN2 were associated with higher risk of colon cancer, particularly in the proximal colon." (PMID 39511728, 2025). "Our analyses revealed a positive association between the LCN2 concentration and CRC that was especially pronounced in women and for (proximal) colon cancer." (PMID 39511728, 2025). "Collectively, LCN2 has been suggested to exert multifaceted roles in the modulation of intestinal and metabolic inflammation, iron homeostasis, as well as in colon cancer initiation and promotion." (PMID 39511728, 2025). "LCN2 inhibits ferroptosis by enhancing GPX4 and SLC7A11 expression and reducing intracellular iron levels, and LCN2 overexpression in colon cancer cells leads to resistance to 5-fluorouracil (5-FU) by inhibiting ferroptosis." (PMID 39396974, 2024). "Expression levels of LCN2 have been found to be high in aggressive subtypes of cancer, including breast, pancreas, thyroid, and colon cancers." (PMID 36926025, 2023). "Compared to KM12C colon carcinoma cells in which LCN2 was downregulated, LCN2-overexpressing cells showed a significant increase in adhesion." (PMID 35053376, 2022). "In situ hybridization revealed a strong signal for LCN2-mRNAs in 10 of the 11 colon cancer samples tested." (PMID 32575507, 2020). "A study of colon cancer showed that high levels of LCN2 in supernatants of primary and metastatic colon cancer cells inversely correlate with their metastatic potential." (PMID 32575507, 2020). "Both LCN2 functions are required for the invasion of colon cancer cells." (PMID 40356520, 2025). "In vitro, experiments have shown that LCN2 mRNA and protein levels were higher in colon cancer samples than in neighboring normal tissue and altering LCN2 in CRC cell lines influenced cell proliferation, epithelial-to-mesenchymal transition (EMT), invasion, and metastasis." (PMID 39596454, 2024).
colon carcinoma (continued). "It should be pointed out LCN2 expression has been shown to elevate the aggressiveness of breast, melanoma, and colon cancers, suggesting that WT bacteria may show reduced anticancer activity in more aggressive cancer types due to higher iron competition." (PMID 38747577, 2024). "In colon cancer, Lipocalin 2 (LCN2) overexpression leads to resistance to 5-fluorouracil." (PMID 38273826, 2023). "Similarly, Hu and coworkers found that LCN2 mediates attachment to basement membrane in colon cancer." (PMID 35053376, 2022). "In addition, two in vitro studies conducted in oral squamous cell carcinoma (OSCC) and colon carcinoma cell line have been shown that lipocalin-2 expression reduces metastatic potential of these cells." (PMID 33542838, 2021). "In addition, for the monitoring of colon cancer related with course, fecal LCN2 has more advantages than fecal CALP in our experimental verification." (PMID 35111677, 2021). "However, several studies have reported that LCN2 suppresses cell migration and invasion in colon cancer and in Ras-transformed mouse mammary cells." (PMID 26840566, 2016). "However, several studies reported that LCN2 suppressed cell migration and invasion in colon cancer and in Ras-transformed mouse mammary cells." (PMID 25940797, 2015). "However, results were not changed suggesting that LCN2 is associated with colon cancer independent of menopausal status." (PMID 39511728, 2025). "In colon cancer cells, LCN2 may function as a metastasis suppressor." (PMID 34202288, 2021). "In multivariable‐adjusted analyses, the IRR [95% CI] per doubling in LCN2 concentration was 1.16 [0.98–1.37] for CRC overall, 1.26 [1.00–1.59] for colon cancer, and 1.08 [0.85–1.38] for rectal cancer." (PMID 39511728, 2025). "In addition, S100A8 and S100A9-activated colon cancer cells showed an upregulation of LCN2 gene expression compared to non-stimulated cells." (PMID 22559235, 2012). "In another study, LCN2 gene expression was upregulated in S100A8 and S100A9-stimulated colon cancer cells compared to non-stimulated cells." (PMID 34072157, 2021).
Cerebral ischemia (29 papers, 2015 to 2025). Restriction of arterial blood supply to the brain associated with insufficient oxygenation to support the metabolic requirements of the tissue. "Moreover, increased Lcn2 expression after cerebral ischemia has been linked to glial activation, neuroinflammation, and blood–brain barrier disruption, all of which contribute to neuronal death." (PMID 37175797, 2023). "Although a large number of studies have supported the pathological role of LCN2 in cerebral ischemia/reperfusion injury, some studies have suggested a different viewpoint." (PMID 40182140, 2025). "The neurotoxic and neuroprotective effects exhibited by LCN2 in cerebral ischemia/reperfusion injury depend largely on the timing and conditions of injury." (PMID 40182140, 2025). "This suggests that changes in LCN2 expression are closely related to the development of injury at specific time nodes after the onset of cerebral ischemia-reperfusion injury, and that LCN2 exhibits more neurotoxic effects at this critical time." (PMID 40182140, 2025). "The in-depth study of these relationships is of great significance to the understanding of the pathological mechanisms of cerebral ischemia/reperfusion injury and the search for precise therapeutic strategies for LCN2." (PMID 40182140, 2025). "Meanwhile, a deeper understanding of the mechanism of LCN2 can also enrich the theoretical system of cerebral ischemia/reperfusion injury and provide new perspectives and directions for basic research in this field." (PMID 40182140, 2025). "For instance, researchers found that inhibiting Lcn-2 expression using Sailuotong capsule effectively prevented neuroinflammation and recognition memory deficits induced by cerebral ischemia." (PMID 38533497, 2024). "proved that CXCL10 upregulated by the JAK2/STAT3 pathway in astrocytes is crucial for Lcn-2-induced cell migration in cerebral ischemia." (PMID 38533497, 2024). "Genetic deletion of Lcn2 significantly reduced brain injury after cerebral ischemia, implying that Lcn2 is a mediator of reperfusion injury and a potential therapeutic target." (PMID 38180614, 2024). "Similar with our results, previous studies have shown that Lcn2 is secreted in response to cerebral ischemia to promote reperfusion injury." (PMID 38180614, 2024). "Changes in Lcn2 expression in GFAP-positive astrocytes indicate that exercise alters astrocytic features after cerebral ischemia." (PMID 36880055, 2023). "The present study identifies LCN2 as a critical regulator of astrocyte pyroptosis following cerebral ischemia/reperfusion injury." (PMID 37353794, 2023). "In summary, the current findings support a pro-pyroptotic role for LCN2 in cerebral ischemia/reperfusion injury." (PMID 37353794, 2023). "LCN2/24p3R mediates astrocyte pyroptosis via NLRP3 inflammasome activation following cerebral ischemia/reperfusion injury." (PMID 37353794, 2023). "Collectively, in cerebral ischemia/reperfusion injury, LCN2 binds to 24p3R on the astrocyte membrane and facilitates NLRP3 activation, which ultimately triggers astrocyte pyroptosis and pro-inflammatory effects." (PMID 37353794, 2023). "Taken together, these findings suggested that LCN2/24p3R mediates pyroptosis in astrocytes via the NLRP3 inflammasome after cerebral ischemia/reperfusion injury." (PMID 37353794, 2023). "LCN2 is shown to be involved in neuroinflammation and neuronal death in various animal brain injury models including cerebral ischemia." (PMID 35440572, 2022). "Experimental findings suggested that LCN2 is expressed in the brain during inflammatory response to cerebral ischemia and hypoxia, and mediates additional brain damage and cognitive decline in VD." (PMID 35027079, 2022). "Enhanced LCN2 expression after cerebral ischemia contributes to neuronal death by promoting glial activation, neuroinflammation, and the BBB disruption." (PMID 35440572, 2022).